STMN1 (stathmin 1)
Diseases named in the same sentence as STMN1 in open-access papers (continued):
Sharing a sentence is not in itself a finding about the gene and the disease.
hepatocellular carcinoma (34 papers, 2011 to 2025). A malignant tumor that arises from hepatocytes. "Collectively, numerous investigations indicate a strong association between the STMN1 gene and hepatocellular carcinoma development, positioning it as a potential diagnostic/prognostic biomarker." (PMID 41403955, 2025). "For example, Stmn1 is overexpressed in hepatoma which is associated with the local invasion, early recurrence, a sign for bad prognosis, and other biological process." (PMID 37726826, 2023). "In humans, PAFAH2 has been linked to intracranial aneurysms while STMN1 has recently been proposed as a biomarker for hepatocellular carcinoma prognosis." (PMID 35782544, 2022). "STMN1 was highly expressed in hepatocellular carcinoma and closely associated with shorter survival time in hepatocellular carcinoma patients." (PMID 34253824, 2021). "We identified six mRNAs (DPYSL4, HOMER1, ABCB6, CENPA, CDK1, STMN1) significantly associated with overall survival in the Cox proportional regression model for hepatocellular carcinoma." (PMID 31790363, 2019). "Furthermore, hsa-miR-193b-3p was found associated to a tumor-suppressor phenotype (by targeting STMN1) in hepatocellular carcinoma and colorectal cancer." (PMID 33333738, 2020). "STMN1 is expressed in various carcinomatosis such as ovarian cancer 89, endometrial cancer 90, cervical cancer 91, hepatocellular carcinoma 92, and bladder cancer 93, and inhibition of STMN1 can reduce cell viability and migration potential." (PMID 38818470, 2024). "Accumulating evidence indicates that STMN1 expression is increased in various human malignancies, such as lung cancer, urinary bladder and hepatocellular carcinoma." (PMID 39711570, 2024). "STMN1 is overexpressed in hepatocellular carcinoma, where it is related to clinicopathological parameters and affects the prognosis of HCC patients." (PMID 36127700, 2022). "In individuals with liver cancer, STMN1 expression was significantly correlated with E2F1/TFPD1 and KPNA2 expression and was associated with poor prognosis in patients with hepatocellular carcinoma." (PMID 36127700, 2022). "STMN1 overexpression plays an important role in the diagnosis and prognosis of hepatocellular carcinoma." (PMID 36127700, 2022). "Meanwhile, these findings also expand new thinking and direction for the mechanism studies of STMN1 in hepatocellular carcinoma." (PMID 36127700, 2022). "STMN1 is an independent predictive factor of poor outcome, it is upregulated in hepatocellular carcinoma and promotes migration, invasion, and EMT by activating PI3K/AKT pathway." (PMID 34556750, 2021). "The result showed that FoxM1 and STMN1 highly express in almost all types of solid tumors in a serial of independent cohorts, including gastric cancer, hepatocellular carcinoma and colorectal cancer." (PMID 33526768, 2021). "The mRNA and protein level of STMN1 were significantly higher in various types of cancer, including colon cancer, lung cancer, pancreatic ductal adenocarcinoma, and hepatocellular carcinoma." (PMID 33201835, 2020). "We further identified the STMN1 gene as a target of thyroid hormone (T3) in the HepG2 hepatoma cell line." (PMID 27934948, 2016). "In the current study, we report that thyroid hormone receptor (THR) expression is negatively correlated with STMN1 expression in a subset of clinical hepatocellular carcinoma (HCC) specimens." (PMID 27934948, 2016). "Regulation of STMN1 expression by miR-223 has been demonstrated in hepatocellular carcinoma by our previous study." (PMID 22470493, 2012). "STMN1 has been reported to be a prognostic biomarker in several cancers including colorectal cancer, esophageal squamous cell carcinoma, hepatocellular carcinoma and oral squamous-cell carcinoma." (PMID 22470493, 2012). "We reported previously that STMN1 is a putative downstream target of miR-223 in hepatocellular carcinoma." (PMID 22470493, 2012).
hepatocellular carcinoma (continued). "However, total STMN1 knockdown resulted in a redistribution of the cell cycle with a decrease in J7 hepatocellular carcinoma cells in the G1 population and a 2-fold increase of J2 cells in the G2/M population." (PMID 40723207, 2025). "Moreover, STMN1 has been demonstrated to be essential for FoxM1-mediated proliferation of cancer cells, such as hepatocellular carcinoma cells, gastric cancer cells and colorectal cancer cells." (PMID 38698443, 2024). "STMN1 has been reported to be an important cytosolic phosphoprotein that is upregulated in all types of cancers and is positively correlated with poor prognosis in hepatocellular carcinoma." (PMID 37514136, 2023). "In hepatocellular carcinoma, STMN1 could promote tumor progression by interacting with YAP1 and triggering the MET pathway." (PMID 35186166, 2022). "Third, although our results suggest that STMN1 is closely associated with immune cell infiltration in hepatocellular carcinoma, we do not have direct evidence that STMN1 is directly involved in immune regulation." (PMID 36127700, 2022). "STMN1 has a significant role in hepatocellular carcinoma diagnosis and prediction." (PMID 36127700, 2022). "Collectively, mounting evidence identifies STMN1 and PRDX1 as potential biomarkers for hepatocellular carcinoma (HCC), further establishing their association with ferroptosis." (PMID 41403955, 2025). "Our study particularly emphasizes the function of STMN1 and PRDX1 as key drivers in hepatocellular carcinoma progression." (PMID 41403955, 2025). "Our findings are consistent with previous research showing that E2F1 can transactivate STMN1 expression in hepatocellular carcinoma, reinforcing the regulatory relationship between the RB/E2F1 axis and STMN1." (PMID 39776361, 2025). "Supporting this, prior research has shown that E2F1 can transactivate STMN1 expression in hepatocellular carcinoma, further supporting the regulatory relationship between the RB/E2F1 axis and STMN1." (PMID 39711570, 2024). "The glycolytic regulators STMN1, MAP17, Homer1, TRIM35, and ABCB6 are considered as potential biomarkers for the prognosis of hepatocellular carcinoma." (PMID 38114977, 2023). "In hepatocellular carcinoma (HCC) and nasopharyngeal carcinoma, the expression of E2F1 and STMN1 was correlated with each other both at mRNA and protein levels." (PMID 35186166, 2022). "Similarly, survival probability in hepatocellular carcinoma was reliably predicted by a glioma prediction model (ACSL3, ACSL6, ACACA, G6PD, SLC1A5, SLC7A11 and VDAC2) and by a risk model with a strong overlap with the genes in the glioma models (G6PD, HMOX1, LOX, SLC7A11, STMN1/Stathmin 1)." (PMID 34926298, 2021). "For instance, endogenous miR-142 and miR-223 from human macrophages were shown to be transferred to hepatocellular carcinoma cells (HCC), which resulted in decreased expression of stathmin-1 and insulin-like growth factor-1 receptor and inhibition of proliferation." (PMID 26861303, 2016). "Two of these potential target genes, stathmin (STMN1) and the insulin-like growth factor 1 receptor (IGF1R), attracted attention because both have been reported to be the target genes of miR-223 in hepatocellular carcinoma and cervical cancer." (PMID 27441818, 2016). "In addition to the role of FOXM1 in cell cycle progression, a recent study showed that FOXM1 is a master regulator of hepatocellular carcinoma metastasis by inducing EMT and increasing cell migration by transcriptionally activating STMN1." (PMID 36151566, 2022).
hepatocellular carcinoma (continued). "In hepatocellular carcinoma cells (HCC) miR-223 was repressed as compared with normal liver tissue by microarrays and STMN1 was the potential target which serves as an oncogene implicating that miR-223 may serve as a tumor suppressor." (PMID 22073238, 2011). "Current studies suggest that upregulation of STMN1 can accelerate the formation and/or progression of hepatocellular carcinoma by activating the YAP1 signaling pathway, and overexpression of STMN1 may be a precursor of hepatocellular carcinoma and can be used as a marker for diagnosis and treatment." (PMID 36127700, 2022).
gastric cancer (21 papers, 2012 to 2024). A primary or metastatic malignant neoplasm involving the stomach. "Bai showed that high STMN1 level was associated with chemo-resistance and poor prognosis in gastric cancer patients." (PMID 29113350, 2017). "Additionally, tubulin STMN1 is up-regulated and has de-stabilizing activity in various tumor tissues, which is associated with the proliferation, invasion, and migration of gastric cancer, ovarian cancer, and HCC." (PMID 35892599, 2022). "In previous studies, both in vivo and in vitro, it has been shown that the proliferation, invasion rate can be reduced by genetically silencing STMN1 with siRNAs in mesothelioma, gastric cancer, colon cancer cell lines." (PMID 37529254, 2022). "Bai found that the high level of STMN1 in patients with gastric cancer was related to chemoresistance and poor prognosis." (PMID 35126478, 2022). "For example, a study that evaluated STMN1 role in both operable and advanced gastric cancers showed that in the operable cohort, STMN1 expression correlated with cancer recurrence, and resistance to adjuvant therapies." (PMID 33828156, 2021). "In gastric cancer, STMN1 expression is related to cancer curability, recurrence, and resistance to adjuvant therapy." (PMID 34253824, 2021). "STMN1 is an oncogene that is a highly conserved cytosolic phosphoprotein, was found to be over-expressed in various types of cancer such as lung, breast, gastric cancer, and HCC." (PMID 34178637, 2021). "Knock-down of STMN1 using siRNA inhibits the proliferation, migration and invasion of gastric cancer cells and slows the growth of xenografts in nude mice." (PMID 28056823, 2017). "In summary, hispidin induces the autophagic and necrotic death of SGC-7901 gastric cancer cells via LMP through inhibiting tubulin polymerization by modulating phosphorylation of microtubule regulatory proteins such as STMN1." (PMID 28460485, 2017). "Silencing STMN1 enhances the sensitivity of gastric cancer cells to docetaxel, with the resistance index reducing to 3.41." (PMID 28056823, 2017). "The reporter constructs containing predicted or mutated binding sites were co-transfected with miR-223 mimic to MKN28 cells, a gastric cancer cell line with relatively low endogenous STMN1 expression." (PMID 22470493, 2012). "We further assessed the STMN1 protein expression by immunohistochemistry and the level of miR-223 by qRT-PCR in 31 primary gastric cancer samples." (PMID 22470493, 2012). "By luciferase reporter assays, we confirmed the specific interaction between miR-223 and STMN1 3′UTR in gastric cancer cells." (PMID 22470493, 2012). "Functional inhibition of STMN1 readily decreased cell proliferation and invasive phenotype, suggesting a protumorigenic role of STMN1 in gastric cancer." (PMID 22470493, 2012). "The negative modulation effect by miR-223 was further substantiated by a significantly reduced STMN1 protein level in gastric cancer cell lines after miR-223 re-expression." (PMID 22470493, 2012). "We further demonstrated that the expression of STMN1 was negatively regulated by miR-223 in gastric cancer cells." (PMID 22470493, 2012). "In this study, we observed a low miR-223 expression level in gastric cancer cell lines and an inverse relationship between miR-223 and STMN1 protein expression." (PMID 22470493, 2012). "To demonstrate the potential suppressive effect of miR-223 on STMN1 expression, we transfected miR-223 to gastric cancer cell lines AGS and MKN7." (PMID 22470493, 2012). "This study is aimed to investigate the functional role of STMN1 in gastric cancer development and mechanisms of regulation of STMN1 in gastric cancer." (PMID 22470493, 2012). "Studies have shown that STMN1 mediates resistance to anti-mitotic chemo-drugs in tumor cells and its inhibition enhances sensitivity to paclitaxel/docetaxel in osteosarcoma, gastric cancer and PCa." (PMID 39711570, 2024).
gastric cancer (continued). "The UGT1A1 polymorphism may be useful to screen the risk population of gastric cancer, while TYMS, TUBB3 and STMN1 may be potential biomarkers for prognosis and chemotherapy guidance." (PMID 28056823, 2017). "Stathmin1 (STMN1) is a candidate oncoprotein and prognosis marker in gastric cancers." (PMID 24456939, 2014). "Western blot analysis confirmed the up-regulation of STMN1 protein in 11 gastric cancer cell lines." (PMID 22470493, 2012). "We finally confirmed that STMN1 is a putative downstream target of miR-223 in gastric cancer." (PMID 22470493, 2012). "The results supported that STMN1 is a putative target of miR-223 in gastric cancer cells." (PMID 22470493, 2012). "The same group demonstrated the oncogenic role of STMN1 in gastric cancer by in vitro inhibition of proliferation, migration and invasion in gastric cell lines by knocking STMN1 down using siRNA, and in vivo inhibition of xenograft tumor growth in nude mice by siRNA transfection." (PMID 22470493, 2012). "STMN1 was upregulated in gastric cancer cell lines and primary gastric adenocarcinomas." (PMID 22470493, 2012). "In this study, we showed that siRNA knockdown of STMN1 inhibited cell proliferation and anchorage-dependent colony formation, impaired invasion and migration ability, induced G1 arrest and late apoptosis in gastric cancer cell lines." (PMID 22470493, 2012). "Our findings supported an oncogenic role of STMN1 in gastric cancer." (PMID 22470493, 2012). "Our findings suggest UGT1A1 polymorphisms may be useful to screen the risk population of gastric cancer and schedule the appropriate pretreatment to improve the overall survival, while TYMS, TUBB3 and STMN1 may be potential biomarkers for prognosis and chemotherapy guidance." (PMID 28056823, 2017). "The expressions of TYMS, TUBB3 and STMN1 were significantly associated with the clinicopathological characteristics of age, gender and family history of gastric cancer, but not with differentiation, growth patterns, metastasis and TNM staging in patients with gastric cancer." (PMID 28056823, 2017). "STMN1 might serve as a prognostic marker and a potential therapeutic target for gastric cancer." (PMID 22470493, 2012). "STMN1 plays a role in cell migration through the EMT process in hypopharyngeal squamous cell carcinoma and gastric cancer." (PMID 35186166, 2022). "It was observed that patients with gastric cancer with CASP 3 expression had a better prognosis than those without; however, in this study CASP3 was unaffected by siRNA-mediated STMN1 silencing." (PMID 37529254, 2022). "Yiqi Jianpi Huaji Decoction can inhibit gastric cancer cell proliferation, induce apoptosis, and increase sensitivity to chemotherapeutic agents by decreasing the expression of TUBB3, MRP, P-gp, and STMN1." (PMID 36210831, 2022). "The biological function of STMN1 was determined by MTT proliferation assays, monolayer colony formation and cell invasion assays using small interference RNA technique in gastric cancer cell lines." (PMID 22470493, 2012). "More importantly, activated STAT3 binds to and inhibits Stathmin 1, resulting in microtubule stability in non-Hodgkin lymphoma and gastric cancer human cell lines, but Stathmin 1 has never been investigated in MPN." (PMID 26356819, 2015). "In poorly differentiated gastric cancer cell lines SNU638 and SNU16, siRNA-induced STMN1 repression could suppress cell proliferation in vitro and in vivo." (PMID 22470493, 2012). "Therefore, the present study was to investigate whether the genes ERCC1, BRCA1, TYMS, RRM1, TUBB3, STMN1 and TOP2A are underlying biomarkers for patients with gastric cancer, which, to our knowledge, has not been performed." (PMID 28056823, 2017).